RECQL4 (RecQ like helicase 4)
Diseases named in the same sentence as RECQL4 in open-access papers (continued):
Sharing a sentence is not in itself a finding about the gene and the disease.
ovarian carcinoma (continued). "Correspondingly, RECQL4 knockdown decreased ovarian cancer cell migration and invasion." (PMID 33014878, 2020). "The effects of RECQL4 during tumorigenesis of ovarian cancer were explored in vivo." (PMID 33014878, 2020). "Functionally, RECQL4 overexpression increased proliferation and invasion of ovarian cancer cells." (PMID 33014878, 2020). "Moreover, upregulated RECQL4 promoted the growth and invasion and reduced olaparib/cisplatin sensitivity of ovarian cancer cells by increasing MAFB expression." (PMID 33014878, 2020). "However, the expression and biological roles of RECQL4 in ovarian cancer remain undefined." (PMID 33014878, 2020). "Using data from TCGA and GTEX, the mRNA expression levels of RECQL4, PRKCL, CCNE1, and ETV5 were found to be increased in ovarian cancer compared to normal FT tissues." (PMID 33014878, 2020). "To explore the mechanism by which RECQL4 drives ovarian cancer malignancy, we performed RNA-seq in HEY cells with RECQL4 knockdown compared to control cells." (PMID 33014878, 2020). "RECQL4 expression was also significantly higher in cisplatin-resistant A2780/DDP cells than in A2780 cells, suggesting a role for RECQL4 in the cisplatin resistance of ovarian cancer." (PMID 33014878, 2020). "High-throughput sequencing was performed to reveal the molecular mechanism of ovarian cancer cells with or without RECQL4 knocked down." (PMID 33014878, 2020).
colorectal cancer (8 papers, 2014 to 2025). A primary or metastatic malignant neoplasm that affects the colon or rectum. "An investigation of the mutation spectrum of cancer-associated genes in patients with early onset colorectal cancer showed that RECQL4 is one of the most often mutated genes." (PMID 34361106, 2021). "In addition, RECQL4 is one of the most often mutated genes in colorectal cancer, and it is upregulated (fold change = 4.10) in colorectal cancer tissues." (PMID 34361106, 2021). "We found that MSI was reduced in the colorectal cancer samples presenting RECQL4 high amplifications (p = 7.86e‐04)." (PMID 39812592, 2025). "RECQL4 is a cancer-driver gene and potential target gene that is regulated by colorectal-cancer-specific enhancers." (PMID 34361106, 2021). "RECQL4 is an example of a cancer-driver gene that is regulated by colorectal-cancer-specific enhancers." (PMID 34361106, 2021). "HiChIP data showed that some target genes of colorectal-cancer-specific enhancers are cancer-driver genes, including RECQL4, and an analysis of Hi-C data indicated that most boundary-changed TADs contain colorectal-specific enhancers." (PMID 34361106, 2021). "The colorectal-cancer-specific enhancer is about 15 kb away from the RECQL4 promoter, and HiChIP data showed interactions between colorectal-cancer-specific enhancers and RECQL4." (PMID 34361106, 2021). "Additionally, the present analysis of RNA-seq data from 275 colon cancer tissues and 349 normal colon tissues showed that RECQL4 is upregulated in colorectal cancer cells." (PMID 34361106, 2021). "Based on the literature and the data analysis in the present study, RECQL4 may be an important target gene of colorectal-cancer-specific enhancers and involved in the progression of colorectal cancer." (PMID 34361106, 2021). "RECQL1, WRN, and RECQL5 mRNA expression have been found to be lower in primary colorectal carcinoma (CRC) samples compared to normal colonic mucosa, while BLM and RECQL4 mRNA levels are increased." (PMID 35782872, 2022). "The copy number gain of ERBB2, RECQL4, and MYC oncogene and MAGEB family has been frequently reported in colorectal carcinoma, as shown in a recent review." (PMID 27481518, 2016).
glioma (7 papers, 2019 to 2025). A benign or malignant brain and spinal cord tumor that arises from glial cells (astrocytes, oligodendrocytes, ependymal cells). "We focused on the consequences of two, recurrent single-point mutations on the enzymatic RECQL4 activity and its functions in human glioma cells." (PMID 41419455, 2025). "WT and mutated RECQL4 were overexpressed in RECQL4 KO glioma cells to study interactions with BLM helicases, cell viability and specific responses to UVC- and chemotherapy-induced DNA damage/repair." (PMID 41419455, 2025). "Biological consequences of RECQL4 mutations in human glioma cells were evaluated in RECQL4 depleted glioma LN18 and LN229 cells generated by the CRISPR/Cas9 gene editing." (PMID 41419455, 2025). "These transcriptomics analyses show that ECM organization is one of the prominent and shared pathways between RQ4 and BLM KO glioma cells, while RECQL4 deficiency has a stronger impact on the cell cycle than BLM deficiency." (PMID 41023983, 2025). "To comprehend the functional consequences of the recurrent RECQL4 mutations in glioma pathogenesis, we combined genetic, biochemical, and cell biology approaches." (PMID 41419455, 2025). "We performed targeted next generation sequencing of 664 cancer-related genes in a large Polish Glioma Cohort and identified novel, potentially pathogenic variants in the RECQL4 gene." (PMID 41419455, 2025). "However, the relevance of RECQL4 gene variants in gliomas and neurofibromatosis-associated neoplasms is unclear, and a possible relation to the alternative lengthening of telomeres (ALT) is currently unproven." (PMID 41317405, 2025). "Notably, these genes belong to similar gene categories as genes which were previously identified as significantly changed in RECQL4 knockout glioma cells suggesting that the RECQL4 variants could be loss-of-function mutations." (PMID 41419455, 2025). "A potential clinical value of RECQL4 lies in its possible prognostic and predictive significance in human cancer, particularly gliomas and MPNST." (PMID 41317405, 2025). "As WP744 induces the apoptotic cells death in glioma cells, the presented results suggest specific functions for RECQL4 and BLM helicases in chemotherapeutics- induced apoptosis." (PMID 41023983, 2025). "The constructs coding for the WT RECQL4 (RQ4wt), RECQL4P532S (RQ4m1) and RECQL4R766Q (RQ4m2) linked to GFP were overexpressed in RECQL4 depleted LN18 and LN229 glioma cells." (PMID 41419455, 2025). "Deletion of RECQL4 in glioma cells (RQ4 KO) induced profound transcriptomic alterations, dissimilar to BLM depletion." (PMID 41023983, 2025). "Taken together, our data suggest that RECQL4 plays a role in the biology of gliomas and MPNSTs, with higher expression in high-grade gliomas and lower expression in MPNSTs, particularly NF1-associated cases." (PMID 41317405, 2025). "Depletion of RECQL4 in LN18 and LN229 glioma cells reduced cell viability by 20% and overexpression of all tested RECQL4 constructs improved cell viability." (PMID 41419455, 2025). "We found slightly decreased survival in RECQL4-knockdown glioma/MPNST cell lines due to increased apoptosis and a significantly increased susceptibility of such cell lines to ATR-kinase inhibitors." (PMID 41317405, 2025). "We determined if RECQL4 variants (which altered interactions with BLM and DNA repair) affect glioma cell responses to TMZ, a main chemotherapeutic in glioma therapy." (PMID 41419455, 2025). "The newly identified RECQL4 mutations affect RECQL4 helicases and their interactions with BLM contributing to glioma progression." (PMID 41419455, 2025). "To study RECQL4 functions in human cells, we employed previously generated human LN18 and LN229 glioma cells depleted of RECQL4 (RQ4 KO)." (PMID 41419455, 2025).
glioma (continued). "The graph shows that depletion of either RECQL4 or BLM has different consequences in different glioma cells, with disturbances of cell cycle related genes noteworthy in RQ4 KO LN229 cells." (PMID 41023983, 2025). "Regarding the predictive value of RECQL4, its depletion in glioma cells conferred increased response to cytotoxic agents." (PMID 41317405, 2025). "RECQL4-depleted glioma cells treated with TMZ and OLA exhibited reduced viability and increased levels of apoptosis markers." (PMID 41023983, 2025). "RECQL4 depletion modestly affected basal glioma cell viability and proliferation, similarly to knock out of the BLM protein." (PMID 41023983, 2025). "RECQL4 depletion had impact on cell cycle of glioma cells following the simultaneous TMZ and OLA treatment." (PMID 41023983, 2025). "RECQL4 or BLM depletion in glioma cells moderately affected cells viability, however LN229 cells displayed minimally increased sensitivity to helicases knock out." (PMID 41023983, 2025). "We and others have shown that RECQL1 and RECQL4 helicases are overexpressed in gliomas which confers poor prognosis due to their abilities to support proliferation and DNA repair." (PMID 41419455, 2025). "Across 10 different queried studies on cBioPortal, genetic alterations in RECQL4 were found in 86/3453 (2.5%) patients with glioma (92/4206 samples, 2.2%)." (PMID 41317405, 2025). "RECQL4 knockdown in glioma and MPNST cell lines resulted in increased apoptosis and susceptibility to ATR-inhibitors." (PMID 41317405, 2025). "We investigated the effect of RECQL4 depletion in glioma cells on cell growth, apoptosis, senescence and polyploidy in the response to combined TMZ and OLA treatment." (PMID 41023983, 2025). "While RECQL4 depletion in human glioma cells with genetic tools slightly impaired cell viability and DNA replication, it induced gross changes in gene expression and increased sensitivity of glioma cells and glioma stem cells to chemotherapeutics." (PMID 33050631, 2020). "We tested if olaparib, a PARP inhibitor, would modulate behaviour of RECQL4-depleted LN18 glioma cells." (PMID 33050631, 2020). "Increased levels of nuclear and cytosolic RECQL4 proteins were detected in GBMs on tissue arrays and in six glioma cell lines." (PMID 33050631, 2020). "To assess changes of mitochondrial transmembrane potential in parental and RECQL4 KO glioma cells, we stained these cells with a fluorescent, potential sensitive probe-JC-1 and measured fluorescence by flow cytometry." (PMID 33050631, 2020). "Depletion of RECQL4 in two glioma lines with the highest RECQL4 level and distinct genetic background (with siRNAs or the validated CRISPR/Cas9 construct) did not affect viability of LN18 cells and weakly reduced viability of LN229 cells." (PMID 33050631, 2020). "We demonstrate that the helicase localises in nuclei and cytoplasm in high grade gliomas, while in normal brains RECQL4 is mostly restricted to cytoplasm." (PMID 33050631, 2020). "Expression of RECQL4 was considerably higher in all six human glioma cell lines in comparison to normal astrocytes." (PMID 33050631, 2020). "Our results support a notion of a strong contribution of the RECQL4 helicase to chemoresistance of glioma cells." (PMID 33050631, 2020). "Knockdown of RECQL4 affected slightly glioma cell proliferation, blocked self-renewal of GCSs, and sensitized certain glioma cells to chemotherapy." (PMID 33050631, 2020). "To study RECQL4 function in human glioma cells, we effectively depleted RECQL4 with two siRNAs in LN18 and U87-MG cells, as confirmed by Western blotting." (PMID 33050631, 2020). "To gain insight into the function of RECQL4 in gliomas, we deleted RECQL4 in human glioblastoma cells and analysed consequences of its deficiency on cell growth, viability, stemness capacity, and cell responses to chemotherapeutics." (PMID 33050631, 2020).
glioma (continued). "RECQL4 was also overexpressed (on both mRNA and protein levels) in 4 established glioma cell lines and 2 GBM-derived cultures in comparison to normal human astrocytes (NHA)." (PMID 33050631, 2020). "We developed glioma sphere cultures from parental and RECQL4 KO LN18 cells and quantified their capacity to self-renew and respond to TMZ." (PMID 33050631, 2020). "Using transcriptomic data from The Cancer Genome Atlas (TCGA) we assessed RECQL4 expression in human gliomas and normal tissues, and we found upregulation of RECQL4 mRNA in glioblastomas (WHO grade IV)." (PMID 33050631, 2020). "RECQL4 expression differed significantly across glioma subgroups (P = 0.012)." (PMID 41317405, 2025). "Moreover, the cytotoxic response of RECQL4 KO glioma cells to TMZ and OLA remained comparable to that of control cells." (PMID 41023983, 2025). "The levels of RECQL4 mRNA were higher in high grade gliomas (HGGs) than in normal brains." (PMID 33050631, 2020). "Herein, we present new insights regarding contribution of RECQL4 helicase to glioma pathobiology." (PMID 33050631, 2020). "We explored if RECQL4 depletion in glioma cells could affect their sensitivity to TMZ or a PARP inhibitor." (PMID 33050631, 2020). "Therefore, RECQL4 is emerging as a novel molecular target for improving individualized glioma therapy." (PMID 33050631, 2020). "This suggests that cell dependency for RECQL4 could be heterogeneous within glioma cell lines and may depend on the status of another oncogenic driver." (PMID 33050631, 2020). "Furthermore, we generated two glioma cell lines with RECQL4 knockout (KO #1,2) using CRISPR/Cas9 genome editing." (PMID 33050631, 2020). "Altogether, we demonstrate that targeting upregulated RECQL4 in malignant gliomas may provide a new strategy for anti-glioma therapy." (PMID 33050631, 2020). "This evidence points to a new role of RECQL4 in glioma stemness and chemosensitivity." (PMID 33050631, 2020). "We found upregulation of RECQL4 expression at mRNA and protein levels in high grade gliomas." (PMID 33050631, 2020). "We demonstrate that targeting RECQL4 overexpressed in glioblastoma could be a new strategy to sensitize glioma cells to chemotherapeutics." (PMID 33050631, 2020). "All these data combined suggest that targeting RECQL4 overexpressed in glioblastoma could be a new strategy to sensitize glioma cells to chemotherapeutics." (PMID 33050631, 2020). "RECQL4 variants were also present in two ALT-positive, ATRX intact NF1-gliomas." (PMID 31462295, 2019). "We analysed the levels of RECQL4 and BLM proteins in LN18 and LN229 glioma cells depleted of respective proteins." (PMID 41023983, 2025). "Functional studies were performed in glioma (U251) and malignant peripheral nerve sheath tumors (MPNSTs) (NF90-8, ST88-14) cell lines following RECQL4 knockdown and treatment with ATR-inhibitors." (PMID 41317405, 2025). "We found markedly upregulated RECQL4 and BLM at mRNA and protein levels in GBMs, while their protein levels were low in lower grade gliomas." (PMID 41023983, 2025). "Depletion of RECQL4 or BLM in human glioma cells by CRISPR/Cas9 editing resulted in profound changes in the transcriptome, reduction of glioma sphere formation and augmented vulnerability to chemotherapeutics." (PMID 41419455, 2025). "In addition, RECQL4 is considered a potential molecular target for cancer therapy given that it correlates with a stem cell phenotype, and its overexpression has been observed to confer resistance to chemotherapy regimens in preclinical settings, including glioma." (PMID 41317405, 2025). "We found RECQL4 and BLM expression upregulated at mRNA and protein levels in GBMs and glioma cell lines." (PMID 41419455, 2025).
glioma (continued). "Knockout of RECQL4 in LN18 and LN229 human glioma cells using the CRISPR/Cas9 editing, resulted in profound changes in the transcriptome, reduced glioma sphere formation capabilities and augmented vulnerability to TMZ." (PMID 41023983, 2025). "While WT LN18 glioma cells were resistant to TMZ or olaparib, RECQL4 KO cells were more sensitive to TMZ." (PMID 33050631, 2020). "We compared transcriptomes of RECQL4- and BLM-depleted LN18 and LN229 glioma cells." (PMID 41023983, 2025). "Overexpression of RECQL4-GFP variants in LN18 cells did not change the appearance of γH2AX and BLM foci in UVC-treated glioma cells." (PMID 41419455, 2025). "In LN229 cells, where most cells die by apoptosis after TMZ, overexpression of RECQL4 variants produced weaker effects on the BLM signal and γH2AX foci in TMZ-treated glioma cells, and the changes were not significant." (PMID 41419455, 2025). "RECQL4 depletion in glioma cells with siRNAs and CRISPR/Cas9 did not affect basal cell viability, slightly impaired DNA replication, but induced profound transcriptomic changes and increased chemosensitivity of glioma cells." (PMID 33050631, 2020). "Viability of LN18 RECQL4 KO glioma cells was not affected, while viability of LN229 KO cells decreased by 30–50% (H respectively)." (PMID 33050631, 2020). "Therefore, we sought to determine how a lack of RECQL4 or BLM in glioma cells would affect cell responses to therapy." (PMID 41023983, 2025). "Moreover, RECQL4 and BLM KO reduced cell proliferation in glioma cells in a range of 10–20%." (PMID 41023983, 2025).
hepatocellular carcinoma (7 papers, 2021 to 2025). A malignant tumor that arises from hepatocytes. "Overexpression of RECQL4 may give hepatocellular carcinoma cells unlimited proliferation potential and promote hepatocellular tumor occurrence." (PMID 40455796, 2025). "Abnormally high expression of RecQ protein-like 4 (RECQL4) has been observed in many cancers, including hepatocellular carcinoma (HCC)." (PMID 34486474, 2021). "In hepatocellular carcinoma cells, RECQL4 overexpression positively correlated with significantly shorter disease-free survival (DFS) and overall survival (OS) times compared with tissue showing lower RECQL4 expression." (PMID 35782872, 2022).